RNU6-36P (RNA, U6 small nuclear 36, pseudogene)
Synonyms: RNU6-36
Gene: Small nuclear RNA gene on chromosome 12 (97,721,716 to 97,721,822, forward strand). Ensembl gene ENSG00000206899.
Homologues: Orthologues: macaque U6 (93% identical), dog U6 (93% identical). Paralogues in human: RNU6-1 (99% identical), RNU6-2 (99% identical), RNU6-3P (99% identical), RNU6-4P (99% identical), RNU6-5P (99% identical), RNU6-6P (99% identical), RNU6-9 (99% identical), RNU6-12P (98% identical), RNU6-13P (98% identical), RNU6-17P (98% identical), RNU6-18P (98% identical), RNU6-25P (98% identical), and 1287 more.